TNF (tumor necrosis factor)
Diseases named in the same sentence as TNF in open-access papers (continued):
Sharing a sentence is not in itself a finding about the gene and the disease.
autoimmune disease (continued). "Our findings extended previous observations that TNF-α inhibitor benefits patients with autoimmune diseases and the therapeutic efficacy of TNF-α inhibitor is better than traditional corticosteroids for patients with immune-related colitis." (PMID 36016934, 2022). "A recent study utilized medical record data, patient samples, and in vivo models to evaluate the impact of inflammation, and TNFα in particular, within the context of autoimmune disease, on lower urinary tract disorders." (PMID 36201508, 2022). "In agreement with the known efficacy of drugs targeting TNF in autoimmune diseases, this gene was among the top-ranking URs in both UC and CD." (PMID 35513850, 2022). "Etanercept, a recombinant soluble receptor to TNF‐α that is used for treating autoimmune diseases, led to significantly reduced periodontal inflammation, infiltration of neutrophils, and iNOS levels in rats with experimentally induced periodontitis." (PMID 34626163, 2022). "In conclusion, our review summarized the regulation and mechanisms of TNF signaling on the recruitment, immunosuppressive function, and chemotaxis of MDSCs in certain tumors, chronic inflammatory diseases, and some autoimmune disorders." (PMID 36358977, 2022). "Sustained high levels of TNF in persistent infections or autoimmune disorders can have detrimental consequences." (PMID 35166321, 2022). "TNFα, which is primarily produced by macrophages, is another pivotal inflammatory mediator in numerous chronic inflammatory and autoimmune diseases." (PMID 35890077, 2022). "In KEGG pathway analysis, the DE-IGs were mainly enriched in pathways of Th1 and Th2 cell differentiation, Th17 cell differentiation, IL-17 signaling pathway, Toll–like receptor signaling pathway, TNF signaling pathway, and autoimmune diseases." (PMID 35676907, 2022). "Additional focus will be placed on the main classes of immune inhibitor therapy utilized in transplant patients and in autoimmune disease including TNF-alpha, Calcineurin, mTOR, purine synthesis antagonists and IMPDH inhibitors." (PMID 36672607, 2022). "The biological effects of the TNF-α/TNF-α receptors axis on autoimmune diseases, including RA, have been intensively explored." (PMID 36012570, 2022). "The main role of the stimuli factor of NETs in autoimmune diseases is assigned to the TNFα/IL-17/IL-23 axis." (PMID 35886575, 2022). "Since biologics targeting TNF (or both TNF and soluble LTα) are used for treatment of autoimmune diseases, it is of great importance to understand all functions mediated by the ligands of TNF/LT system in normal physiology." (PMID 35741098, 2022). "Considering the number of patients who are treated with TNF inhibitors worldwide, secondary autoimmune disease development is a significant medical problem." (PMID 35104241, 2022). "An inverse and interdependent relationship between TNF-α and interferon levels, and the increase in interferon levels that characterizes the onset of autoimmune diseases have been proposed." (PMID 34802085, 2022). "TNF-α is considered to be an important pro-inflammatory cytokine in T cell-mediated autoimmune diseases, and its biological effects in MG include induction of IL-6, activation of B cells, and priming of AChR-specific T cells." (PMID 36303555, 2022). "Tumor necrosis factor α (TNFα), an important clinical testing factor and drug target, can trigger serious autoimmune diseases and inflammation." (PMID 35621957, 2022). "TNF blocking agents have side effects that promote the onset of MS and other autoimmune diseases such as RA." (PMID 35163260, 2022). "TNF-α is a classic pro-inflammatory factor, which is not only increased in most autoimmune diseases, but also significantly increased in the elderly and related degenerative diseases." (PMID 35527996, 2022). "Disease conditions, such as local and systemic infections, septic shock, degenerative arthritis and other autoimmune diseases appear to be regulated by TNF-α and IL-1β." (PMID 36678378, 2022).
autoimmune disease (continued). "In UC, TNF had high ranks, which is consistent with drugs targeting TNF being extensively clinically used for autoimmune diseases." (PMID 35513850, 2022). "TNFα is an important pro-inflammatory cytokine involved in acute and chronic inflammation, autoimmune diseases and tumors." (PMID 36294967, 2022). "Recombinant antibodies targeting TNF-α have been commercially available for years, to treat a wide array of autoimmune diseases." (PMID 36048826, 2022). "As a main regulatory cytokine, TNF plays a central role in inflammation and autoimmune diseases, and anti-TNF therapy dramatically improves clinical symptoms and quality of life in AD patients." (PMID 36678712, 2022). "First recognized as an endogenous soluble factor that induces necrosis of solid tumours, TNF became increasingly important as pro-inflammatory cytokine being involved in the immunopathogenesis of several autoimmune diseases." (PMID 35122118, 2022). "As autoimmunity is based on an imbalance between pro-inflammatory and anti-inflammatory stimuli, cytokines such as IL1, IL36, and TNF alpha and T cell related factors are important in autoimmune diseases." (PMID 35163260, 2022). "In fact, it was previously revealed in mice encoding a genetic deletion of this gene shall exacerbate the autoimmune disease EAE by increased production of proinflammatory cytokines such as TNF-α, IL-6, and IL-17 in the CNS and lymph nodes." (PMID 34980262, 2022). "TNF-α is thought to contribute to the development of autoimmune diseases by promoting expression of other proinflammatory cytokines, recruitment of inflammatory cells and damage of organs." (PMID 35432384, 2022). "Further studies on patients with moderate-to-severe decreased cardiac function to investigate the synergy of anti-TNF and heart failure are needed; likewise, other patients with autoimmune diseases, including CD, who are receiving ADA, should be considered." (PMID 36687438, 2022). "There are several approved TNFα inhibitors and one IL-1R antagonist used to treat autoimmune diseases, highlighting the importance of this pathway in chronic inflammatory diseases." (PMID 33776573, 2021). "On this regard, TNF-α inhibitors have been successfully used to control several autoimmune diseases including ankylosing spondylitis, rheumatoid arthritis, polyarticular juvenile idiopathic arthritis, psoriasis as well as psoriatic arthritis." (PMID 35185598, 2021). "Currently, clinically approved TNF-α inhibitors have shown noticeable potency in a variety of autoimmune diseases, and novel TNF-α signaling inhibitors are being clinically evaluated." (PMID 33800290, 2021). "TNFα is a pleiotropic cytokine that has pivotal roles in prolonged inflammation and autoimmune diseases." (PMID 34222497, 2021). "Many established autoimmune-disease drug targets, such as TNF blockers, IL23/IL12 antagonists, and CTLA4 agonists, have either prospectively or retrospectively been shown to reside in GWAS loci of autoimmune diseases." (PMID 33798443, 2021). "Among the variables studied, the MFI of MAIT cells after staining was lower for TNF-α and GzB in women with long-term type 1 diabetes and another autoimmune disease compared with women with long-term type 1 diabetes." (PMID 34350463, 2021). "Th17 cells are a subset of CD4+ helper T cells, which are widely believed to induce inflammation in the pathogenesis of autoimmune diseases by producing cytokines such as IL‐17, TNF‐α, and IL‐6." (PMID 33728820, 2021). "These TH17 cells secrete large amounts of pro-inflammatory cytokines GM-CSF, TNF-α and IL-2 that coincided with severe forms of autoimmune disease such as experimental autoimmune encephalomyelitis (EAE)." (PMID 34334139, 2021). "Proinflammatory cytokines such as IL-1β, IL-6, and TNF-α, which play crucial roles in the development of inflammatory diseases, are also involved in the innate immunity and autoimmune diseases." (PMID 34824594, 2021).
autoimmune disease (continued). "Somewhat unexpectedly, the most important practical application of TNF biology in medicine is anti-TNF therapy in several autoimmune diseases." (PMID 34054827, 2021). "The use of biologic drugs such as anti-TNF agents has dramatically transformed the treatment of autoimmune diseases, including IBD." (PMID 33429950, 2021). "A prolonged exposure to TNFα and GC spreading are characteristic features of many lymphoid lesions, including autoimmune diseases and some lymphomas." (PMID 34222497, 2021). "Tumor necrosis factor (TNF)-α bioactivity is a prerequisite in several inflammatory and autoimmune disease models." (PMID 33924332, 2021). "TNF-α is mainly produced by activated monocytes/macrophages and participates in the pathological damage of multiple autoimmune diseases." (PMID 34654474, 2021). "The mRNA levels in some genes have been identified as pharmacogenomic biomarkers of the activity of anti-TNF drugs in the inflamed tissues of adults diagnosed with IBD or other autoimmune disorders." (PMID 33429950, 2021). "This is in contrast to studies reporting that TNF-α can activate T cells and the production of autoantibodies and even selectively destroy autoreactive T cells in several autoimmune diseases." (PMID 33572870, 2021). "TNF-α is known to trigger cell activation, migration, or proliferation against pathogens, and is involved in the pathogenesis of inflammatory and autoimmune diseases." (PMID 35095906, 2021). "As post-infection autoimmune diseases involve a persistent inflammatory reaction, tumor necrosis factor-α (TNF-α) was one of the earliest genes to be studied in RHD, showing strong associations in different populations." (PMID 33842495, 2021). "Bidirectional function of TNF-α is validated to amplify in autoimmune diseases, especially the deleterious effect." (PMID 33746606, 2021). "For example, the TNF-α concentration in the saliva of healthy humans is lower than 3 pg ml−1 and increases to about 30 pg ml−1 in the saliva of patients with severe autoimmune diseases." (PMID 34621727, 2021). "Although atrosab has shown promise in preclinical trials, it has yet to pass clinical trials in human subjects before being recruited as an approved treatment option for MS and other TNF-mediated autoimmune disorders." (PMID 34804701, 2021). "We have previously shown that both anti-CD28 and soluble TNFα inhibited the expression of PTPN22, a gene that is associated with several autoimmune diseases, but only anti-CD28 promoted the production of IL-17A/F in anti-CD3 stimulated PBMCs." (PMID 34301319, 2021). "Tumour necrosis factor alpha (TNF-α), a pleiotropic cytokine produced by activating monocytes/macrophages in the inflammatory process, is considered an important biomarker of autoimmune diseases." (PMID 34621727, 2021). "A dysregulated inflammatory process characterizes most autoimmune diseases, and tumor necrosis factor alpha (TNFα) is an important inflammatory factor." (PMID 34886761, 2021). "Etanercept is a tumor necrosis factor alpha (TNF-α) inhibitor chronically used to treat autoimmune diseases." (PMID 35185598, 2021). "Two pathways commonly dysregulated in autoimmune diseases and cancer are tumor necrosis factor alpha (TNFα) and interleukin 1 beta (IL-1β) signaling." (PMID 33776573, 2021). "Natural products (NPs) have played a significant role in drug discovery for diverse diseases, and numerous attempts have been made to discover promising NP inhibitors of tumor necrosis factor α (TNF-α), a major therapeutic target in autoimmune diseases." (PMID 34572435, 2021). "The impact of TNF-α signaling on each type of autoimmune disease will be introduced in this review, as well as the evaluation of current TNF-α inhibitors utilized as therapeutic drugs against autoimmune diseases." (PMID 33800290, 2021). "In this review, we briefly introduce the impact of TNF-α signaling on autoimmune diseases and its inhibitors, which are used as therapeutic agents against autoimmune diseases." (PMID 33800290, 2021).
autoimmune disease (continued). "Although there are numerous studies on TNF-α in various autoimmune diseases, the pathological mechanism and research progress of TNF-α in uveitis have not been reviewed." (PMID 34795583, 2021). "TNF-α blockade quickly became the “standard of care” for these autoimmune diseases due to their effectiveness in controlling disease and decreasing patient’s adverse risk profiles compared to broad-spectrum immunosuppressive agents." (PMID 33854514, 2021). "In autoimmune diseases, high circulating levels of TNFα suppress the adiponectin secretion by adipocytes and predict the development of type 2 diabetes." (PMID 34959666, 2021). "Th1‐biased immune responses are often implicated in autoimmune disease and increased production of the pro‐inflammatory cytokines IFN‐γ and TNF‐α." (PMID 33970540, 2021). "IL-17 acts in conjunction with TNF and IL-1 and plays a critical role in autoimmune diseases and allergic responses." (PMID 34334139, 2021). "Among these cytokines, tumor necrosis factor alpha (TNFα) has attracted most attention as it has been found to be deregulated in patients with autoimmune diseases including RA." (PMID 34777329, 2021). "This pool of mononuclear macrophages produces large quantities of proinflammatory cytokines such as TNF, IL-6, and 1-β, leading to autoimmune disease severity." (PMID 33946736, 2021). "Autophagy induced by TNF-α is another adverse factor affecting MSCs’ effects on autoimmune disease, and our data suggested the anti- autophagy function of sTNFRII-MSC." (PMID 34627365, 2021). "Anti-TNFα therapy reduced vascular inflammation and reduced arterial stiffness in patients with autoimmune diseases." (PMID 33532132, 2021). "Furthermore, anti-TNF drugs can lead to severe side-effects, including common and opportunistic infections, reactivation of latent tuberculosis, increased susceptibility for development of additional autoimmune diseases, demyelination diseases, and an increased risk to develop lymphomas." (PMID 34305946, 2021). "In this review, we included all the studies related to the pathophysiological mechanisms of TNF signaling in neurodegenerative diseases, the use of TNF alpha-blockers in other autoimmune diseases, the adverse effects, and the efficacy of TNF alpha-blockers." (PMID 34804701, 2021). "At inflammatory sites, high levels of proinflammatory cytokines such as GM-CSF and TNF α can enhance the release of ROS, and anti-TNF α therapy is very beneficial in RA, As, Crohn’s disease and other autoimmune diseases and infectious diseases." (PMID 34335600, 2021). "TNF signaling plays an important role in inflammatory and autoimmune diseases and participates in biological processes, including cell proliferation, apoptosis, and differentiation." (PMID 34521820, 2021). "As an outcome, there was a huge success of anti-TNF-α blockers, which became the “standard of care” for many autoimmune diseases." (PMID 33854514, 2021). "This autoimmune disease is characterized by inflammation with an increased expression of inflammatory cytokines such as TNF-α, leading to severe bone destruction mediated by osteoclasts." (PMID 34620220, 2021). "Currently, anti-TNF therapy is a primordial pharmacotherapy involved in the treatment of most autoimmune diseases." (PMID 34684029, 2021). "Given the data we have uncovered, as well as TNFα/IL-1β's therapeutic relevance in autoimmune diseases and cancer, it would be beneficial to examine miR-708's ability to reduce autoimmune-related inflammation and oncogenesis." (PMID 33776573, 2021). "Proinflammatory factor tumor necrosis factor-α (TNF-α) is an important inflammatory mediators in tumor microenvironment and autoimmune diseases, it is highly expressed in many solid tumors and tumor microenvironment, showing a tumor promoting role." (PMID 33854637, 2021).
autoimmune disease (continued). "The non-CHD indications of clinically used drugs included dyslipidemias (PPARA), type 2 diabetes (PPARG and NDUFA13), autoimmune diseases (TNF), neoplasms (RAF1 and PSMA5), circulatory disorders (ABCA1, PLG, ITGB3, and F2), and alcohol-dependency (ALDH2)." (PMID 34675202, 2021). "On the contrary, systemic inhibition of TNF demonstrated striking therapeutic effects in the treatment of several autoimmune diseases." (PMID 33917839, 2021). "While TNF-α depletion halted the disease progression and promoted repigmentation in vitiligo, 18 of 5,928 patients developed vitiligo de novo when TNF-α inhibitors were administered for other autoimmune disorders." (PMID 33335528, 2020). "For instance, TNF - α is a pro-inflammatory cytokine, which is involved in the pathogenesis of several autoimmune diseases and also stimulates the secretion of other inflammatory cytokines." (PMID 32637701, 2020). "Antibodies against TNF have been used for years as treatment for autoimmune diseases such as rheumatoid arthritis and inflammatory bowel disease." (PMID 33193418, 2020). "The invention claimed compounds as interleukin 17 (IL-17) inhibitors and tumor necrosis factor alpha (TNFα) inhibitors and further related to their use in the treatment of inflammatory or autoimmune diseases and other related pathologies." (PMID 32751358, 2020). "This blockage of TNF in patients with autoimmune disease leads to a rapid decrease in IL-1, IL-6, and subsequent leukocyte trafficking." (PMID 33193418, 2020). "Despite promising results in other autoimmune diseases, anti-TNF therapy has proven unsuccessful in MS." (PMID 33066433, 2020). "TNF-α inhibition has been a successful therapeutic strategy for autoimmune diseases such as rheumatoid arthritis, plaque psoriasis, Crohn’s disease, and ulcerative colitis." (PMID 33233734, 2020). "In this nested case-control study, we evaluated patients with autoimmune diseases with an FDA–approved indication for TNF inhibitor use." (PMID 32421186, 2020). "This case-control study examines the inflammatory CNS event outcome among patients with an autoimmune disease who were treated with tumor necrosis factor inhibitors." (PMID 32421186, 2020). "Th1 cells secrete tumor necrosis factor-α (TNF-α), IL-2, IFN-γ, which involve in the activation of macrophages and CD8+ T cells, associated with organ-specific autoimmune diseases." (PMID 30796732, 2020). "Oddly, patients receiving anti-TNFα blockers for various autoimmune diseases have been reported to paradoxically develop AA even though TNFα is a cytokine well-known to contribute to the pathogenesis of AA35,156." (PMID 32411394, 2020). "Although TNF inhibitors are used for other autoimmune diseases, including systemic lupus erythematosus (SLE) and Sjögren’s syndrome, data have not been disaggregated and analyzed to determine if there are male-female differences in treatment responses." (PMID 32366281, 2020). "Study the incidence of serious infections in HIV-infected patients who received TNF-α inhibitor therapy for concomitant autoimmune diseases among different stratified viral loads." (PMID 33209528, 2020). "Tumor necrosis factor blockers have demonstrated their clinical effectiveness, are successfully used to treat autoimmune diseases and are under the top-selling biologics world-wide." (PMID 32528961, 2020). "Many TNF-α antagonists, icluding Infliximab, Certolizumab, Etanercept, Golimumab, and Adalimumab have revolutionized for therapeutic management of different autoimmune diseases, notably rheumatologic inflammatory diseases." (PMID 33262408, 2020). "Adalimumab is a biological agent targeted at TNF-α, which has been proved to have good efficacy in other autoimmune diseases." (PMID 32724829, 2020). "The in silico analysis has verified the molecular effect of the rs1800629 SNP on TNF-α transcription with a potential subsequent effect on the pathogenesis of many autoimmune diseases." (PMID 33370782, 2020).